IL1R1 (interleukin 1 receptor type 1)
Diseases named in the same sentence as IL1R1 in open-access papers (continued):
Sharing a sentence is not in itself a finding about the gene and the disease.
tumor (continued). "Targeting this pathway with anti-IL-1α antibodies or the IL-1 receptor 1 (IL-1R1) blocker anakinra at the onset of tumor formation not only retards tumor progression but also restores myelopoiesis in older mice." (PMID 40765820, 2025). "We analyzed the expression of IL-1 signal-related genes in epithelial cells, and the results showed that the expression of Il1r1 was decreased in tumor cells after the deletion of IL-1R2, suggesting a decreased IL-1 signaling in Il1r2−/− tumor cells." (PMID 40767963, 2025). "It is demonstrated that combining the IL1R1 inhibitor anakinra with radiation can mitigate the effects of radiation on tumor cells." (PMID 39903771, 2025). "We detected that TNFRSF12A, IL1R1, ELN and CYP26B1 were unfavorable prognostic factors that were overexpressed in tumor tissues and associated with poor survival in the TCGA-BLCA cohort." (PMID 38216619, 2024). "Blocking IL-1β also helped to reduce tumor progression, but combining IL-1α/IL-1β blockade or targeting them both using the IL-1R1 antagonist anakinra most effectively disrupted tumor initiation." (PMID 39236155, 2024). "Further analysis of the differential expression of IL-1 family and related genes in normal tissues and HPV- and HPV+ tumor tissues revealed that IL-1α, IL-1β, IL1R1, IL1R2, IL1RL1, IL1RAP, IL1F10, IL-18 and CASP1 were highly expressed in HPV- tumors." (PMID 39461030, 2024). "Infiltration of tumour-associated macrophages (TAM) was also sensitive to the length of tumour cell telomeres and highly correlated with IL1R1 expression." (PMID 39728924, 2024). "To check if our findings were clinically relevant, we used TNBC tumour samples to characterise telomere length and IL1R1 expression." (PMID 39728924, 2024). "The various cell types that express IL-1R1 control the function of IL-1 signaling at various stages of cancer, which in some cases results in divergent roles in tumor development." (PMID 38602556, 2024). "(G) mRNA expression of IL1R1 in xenograft tumours (HT1080 or HT1080-LT cells); 18 S was used for normalisation." (PMID 39728924, 2024). "In RCC mouse models, the blockade of IL-1/IL-1R pathway with recombinant IL-1RA or Il1r1 knockdown, inhibits tumor growth and TAMs pro-tumor phenotype." (PMID 38397187, 2024). "Collectively, we found that nanosystems did not affect Th17 cell viability, were internalized through ANK/IL-1R1 interaction, and exerted their modulatory effects primarily by inhibiting pro-tumor IL-17, while preserving anti-tumor IFN-γ." (PMID 39125655, 2024). "Next, along with IL1R1, a curated set of pro- and anti-inflammatory cytokines commonly studied concerning tumour immunity was screened in TNBC tissue (12 patients- 6 long telomere, 6-short telomere)." (PMID 39728924, 2024). "Although IL-1α and IL-1β both signal through the same ubiquitously expressed receptor (IL-1R1) on all cells, the resulting effects on tumor biology can be distinct and tissue specific." (PMID 37733448, 2023). "Next, the expression profiles of CAFs with high or low levels of IL1R1 in response to the presence of tumor cells were determined." (PMID 37460545, 2023). "Strikingly, and in agreement with the results obtained in the ColVIcre+IL1R1fl/fl mice, we observed a reduction in tumor growth upon IL1R1 blockade." (PMID 37460545, 2023). "To determine the importance of IL1R1 in promoting co‐culture‐induced tumor growth and cancer metastasis, we used shRNA to knockdown the expression of IL1R1 in 231‐GFP cells." (PMID 37551997, 2023). "Using patient-derived CAF and tumor spheroid cultures, we confirmed that CAFs expressed more IL1R1 than tumor cells." (PMID 37460545, 2023). "Collectively, our study highlights the importance of IL1R1 and IL-1β signaling in the fibroblast compartment, especially in regard to driving immunosuppression and tumor growth." (PMID 37460545, 2023).
tumor (continued). "The increase in tumor-promoting gut bacteria in the mouse model of colorectal cancer induced by the APC gene upregulated IL-1R1 expression on T cells, which in turn stimulated the production of IL-17 and IL-22, thereby promoting tumor progression." (PMID 37680632, 2023). "Animal results showed that knockdown of IL1R1 significantly reduced the tumor size by 49% and the tumor weight by 53.6% of co‐cultured 231‐GFP cell‐derived xenograft tumors in NOD/SCID mice." (PMID 37551997, 2023). "IL1R1 signaling can modulate various aspects of tumor biology, such as angiogenesis, invasion, metastasis, immunity and drug resistance." (PMID 37207166, 2023). "Genetic loss or locally antagonizing IL-1β/IL-1R1 leads to reduced MDM infiltration, diminished tumor growth, and reduced exhausted CD8+ T cells and thereby extends the survival of tumor-bearing mice." (PMID 37733448, 2023). "IL-1R1 ablation in T cells dampens the production of IL-17 and IL-22 that promotes tumor-elicited inflammation and tumor progression." (PMID 36932407, 2023). "In addition, genes such as IGF143 have been associated with increased CRC tumor growth and aggressiveness, suggesting that the IL1R1+ iCAF subtype may possess other potential pro-tumorigenic effects in addition to its elevated IL1R1 expression and IL-1β signaling." (PMID 37460545, 2023). "Cxcl1 transcription in CAFs—another key iCAF marker—was similarly induced nearly 22-fold following co-culture with tumor-infiltrating neutrophils, and significantly abrogated with either IL-1β or IL-1R1 inhibition (all p<0.0001)." (PMID 36107485, 2022). "Intratumoural IL1R1+ and IL1R1− Treg cells (from n = 3 tumours) formed separate clusters (orange and blue, respectively), distinct from blood Treg cells." (PMID 35545675, 2022). "From this analysis, we found that macrophage-derived IL1B showed a high and wide regulatory potential to these EMT genes, putatively via the receptor IL1R1 expressed in tumor cells." (PMID 36423636, 2022). "Post efferocytosis, we observed a significant increase in the transcriptional activation of Il1b and Il1r1 as well as a modest change in the mRNA levels of Nlrp3, consistent with our bulk RNA-seq analysis from sorted human tumor-derived CD11b+ cells." (PMID 36439171, 2022). "Follow-up experiments confirmed these computational predictions: IL1R1+ Treg cells in the tumour showed substantial clonal expansion, superior immunosuppressive function and hallmarks of recent TCR stimulation." (PMID 35545675, 2022). "Compared with the WT fibroblast group, the Il1r1−/− fibroblast group showed inhibition of tumor cell growth following coimplantation." (PMID 35410257, 2022). "We found that 10–20% of IL1R1+ Treg cells in HNSCC tumours were clonally expanded, with the top 10 clones in the tumour making up more than 5% of the total number of cells recovered for some donors." (PMID 35545675, 2022). "Inhibiting IL-1 signalling with the IL1β specific antibody, Canakinumab, or the IL1R1 antagonist Anakinra almost eliminates bone metastases but has adverse effects on tumours growing outside of the bone and immune regulation." (PMID 36230739, 2022). "Stimulation of Treg cells with anti-CD3 and anti-CD28 coated beads optimized for T cell activation led to a more pronounced increase in IL1R1 expression (up to 50% of blood Treg cells and IL1R1- tumour Treg cells)." (PMID 35545675, 2022). "It is associated with IL-1 receptor (IL-1R1), which participates in CRC-associated inflammation and tumor progression." (PMID 35794137, 2022). "IL1R1 expression on blood Treg cells and IL1R1− tumour Treg cells was induced after 24 h of stimulation with anti-CD3, anti-CD28 and anti-CD2 beads (anti-CD3/CD28/CD2 beads)." (PMID 35545675, 2022). "DFT2 cells express comparable levels of STAT3 to DFT1, which do not change upon treatment with IFNγ in either cell line, and lower levels of Interleukin 1 Receptor, Type 1 (IL1R1), which is upregulated by both tumours in response to IFNγ." (PMID 34780568, 2021).
tumor (continued). "Taken together, these data suggest that tumour-derived IL-1B signalling, via IL1R1 activation, inhibits primary tumour growth, while enabling tumour invasion." (PMID 34290237, 2021). "Using syngeneic IL-1B/IL1R1 knock out mouse models in combination with genetic manipulation of tumour cells to overexpress IL-1B/IL1R1, we found that IL-1B signalling elicited an opposite response in primary tumours compared with bone metastases." (PMID 34290237, 2021). "The myeloid-specific deletion of IL-1R1 increased tumor multiplicity and size in an APC mouse model." (PMID 33578830, 2021). "The tumor-promoting effect of IL-1R1 deletion was inhibited via ABX pre-treatment, suggesting a role for the microbiota in the tumorigenic effects of IL-1." (PMID 33578830, 2021). "They demonstrated that iCAF formation is induced by tumor-secreted IL-1 that activates a LIF/JAK/STAT-dependent cytokine cascade, whereas tumor-secreted TGF-β antagonizes JAK/STAT signaling by IL-1R1 downregulation and promotes differentiation into myCAF." (PMID 35004765, 2021). "In order to provide further insights into the metastatic gene expression profile triggered by hypoxia through the IL-1β/IL1R1 axis, we performed a TaqMan Gene Expression Assay, which consists of a Human Tumor Metastasis Array." (PMID 32778144, 2020). "Pre‐treatment with the IL‐R antagonist, anakinra or siRNA to IL‐1R1 significantly reduced chemokine secretion from NTF stimulated with conditioned medium from HPV‐negative tumour cells or recombinant IL‐1β (p < 0.05)." (PMID 30191960, 2019). "T cell specific ablation of IL-1R1 similarly decreased tumor-elicited inflammation dependent on IL-17 and IL-22, thereby reducing CRC progression." (PMID 31231372, 2019). "The pro-inflammatory cytokine, IL-1β, provokes the epithelial–mesenchymal transition (EMT) of tumor cells due to activation of the IL-1β/interleukin 1 receptor type 1 (IL-1RI)/β-catenin signaling pathway and recruits additional immune cells to the tumor site." (PMID 31861801, 2019). "Analysis of epithelial cell specific IL-1R1 deletion revealed a decrease in CRC tumor multiplicity, slower proliferation of early tumor seeds, and decreased activation of NF-κB." (PMID 31231372, 2019). "To investigate the selective effects of IL-1a and IL-27 on certain tumor cell lines, we quantified mRNA expression for the subunits of the IL-1a (IL1R1, IL1RAP) and IL-27 receptors (IL27RA, IL6ST)." (PMID 31730010, 2019). "We observed that IL-1R1 is overexpressed in a distinct subpopulation of patients categorized as progressive disease (PD), defined as an increase in tumor burden upon CTX treatment." (PMID 30261609, 2018). "High primary tumour burden was found in both IL-1R1 −/− and IL-1A −/− mice, and this phenotype was independent of caspase-1/-11." (PMID 29760166, 2018). "Consistent with IL-1R1 expression on endothelial cells, IL-1 promotes tumor angiogenesis, which is critical for tumor growth." (PMID 28450382, 2017). "We verified the efficacy of anti-IL-1R1 in vivo by measuring the relative expression of IL-1-responsive genes and saw a significant reduction in the expression of Il6, Il1b and Ptgs2 in tumours from anti-IL-1R1-treated mice relative to IgG-treated mice." (PMID 27708283, 2016). "Hodgkin and Reed-Sternberg (HRS) cells of all cases expressed low IL-1R1 transcript levels in some tumor cells, and high levels of IL-1R2 in large proportions of HRS cells." (PMID 26406983, 2015). "Allograft tumor growth was slower in Il17a−/−, Il1r1−/−, Nlrp3−/−, and Casp1−/− mice after chemotherapy treatment, demonstrating all elements in this pathway play a part in tumor protection although the exact mechanism is unclear." (PMID 24795727, 2014). "Yet, in opposition to their study, we did not observe any effect of IL-1β treatment on sHLA-E production by tumor cells, probably due to a low expression of IL-1 receptor (IL-1R1) by the tumor cell lines tested in our study." (PMID 21712991, 2011).
tumor (continued). "Leveraging advanced bioinformatics techniques, the identification of 12 crucial genes (ETNK1, BICRA, IL-1R1, KDM3A, ARID2, GSK3β, EZH2, NOTCH1, SMARCA4, FOS, CREB1, CASP3) associated with the tumor-suppressing miR-101-3p network stands out as a notable achievement." (PMID 40074445, 2025). "Similarly, upregulation of IL-1R1 expression in human HCC tissues was found to correlate with tumor size and higher TNM stage." (PMID 39621069, 2024). "IL1B and IL1R1 expression was significantly low in the case of tumours/cells with relatively long telomeres and notably consistent across clinical tissue, organoids, xenografts and cells, in contrast to the other cytokines which showed model-specific variation." (PMID 39728924, 2024). "(G) TRF2, IL1R1 levels from xenograft tumours in NOD-SCID mice (control or doxycycline-induced TRF2 in HT1080 cells; N=6 mice in each group) by immuno-flow cytometry; mean fluorescence signal from individual tumours in control or TRF2-induced tumours plotted in adjacent graphs." (PMID 39728924, 2024). "In tumor tissues, IL-1α, IL-1β, IL1R1, IL1RL1, IL1F10, IL33, CASP1, and AIM2 are highly expressed." (PMID 39461030, 2024). "This further supports the beneficial effects of hepatic IL-1R1 inhibition with respect to tumor formation, which might be, at least in part, overridden by chronic metabolic inflammation induced by HFD." (PMID 39621069, 2024). "To determine how the immune system could be modulated by IL1R1+ iCAFs, we further subclustered tumor myeloid and T cells of the Lee and Qian scRNA-Seq datasets to identify macrophages, CD4+ and CD8+ T cells as well as Tregs." (PMID 37460545, 2023). "Here, we show that PDGFB-driven GBM cells induce the expression of the potent proinflammatory cytokine IL-1β in MDM, which engages IL-1R1 in tumor cells, activates the NF-κB pathway, and subsequently leads to induction of monocyte chemoattractant proteins (MCPs)." (PMID 37733448, 2023). "Furthermore, both a fibroblast-specific IL1R1 knockout and IL-1 receptor antagonist Anakinra administration reduce tumor growth in vivo." (PMID 37460545, 2023). "Similarly, another study also identified two types of tumor ECs: INSR+ tumor EC (INSRhiHSPG2+PLVAP+) and ACKR1+ tumor EC (ACKR1+SELP+IL1R1+) in early-stage lung cancer that radiologically manifests as part-solid nodules." (PMID 37187731, 2023). "However, when IL-1R1 is knockout in neutrophils, bacterial invasion into tumors potentiates inflammation allowing for enhanced tumor progression." (PMID 36932407, 2023). "Local antagonism of IL-1β or IL-1R1 prolongs the survival of tumor-bearing mice." (PMID 37733448, 2023). "The effector cytokines of inflammasomes can be different when it comes to spontaneous breast cancer mice models where genetic blockage of IL-1α/IL-1R1 signal develops higher tumor burden and increased mortality rate implying similar roles of IL-1α, IL-1β, and IL-18 in tumorigenesis." (PMID 36932407, 2023). "Notably, the secreted IL-1β/IL-18 activates downstream signaling pathways by binding to their respective receptors (IL1R1, IL-18Rα, and IL-18Rβ) on tumor cells, therapy performing multiple functions in tumor progression." (PMID 36823153, 2023). "Given the role of IL1R1 in tumor progression, our findings suggest that preventing the binding of IL1α and its receptor by using antibodies against IL1α or IL1R1 could be new therapeutic strategies to reduce malignancy of TNBC." (PMID 37551997, 2023). "The sub‐clustering of ECs revealed six subtypes, including extra‐alveolar capillary EC (cEC) (FCN3+EDN1+PLVAP+), alveolar cEC (HPGD+EDNRB+IL1RL1+), arterial EC(GJA5+FBLN5+DKK2), lymphatic EC (CCL21+TFF3+FABP4), INSR+ tumour EC (INSRhiHSPG2+PLVAP+), and ACKR1+ tumour EC (ACKR1+SELP+IL1R1+)." (PMID 35184398, 2022). "Furthermore, ALDH+/IL-1R1+ BCa stem cells are tumor-initiating and show enhanced clonogenicity that can be attenuated with anakinra." (PMID 35626710, 2022).
tumor (continued). "Whereas AL139147.1 showed a novel positive correlation with ENTPD1 (CD39) and IL1R1, which are involved in tumor immune cells infiltration and tumor microenvironment alteration; AC131391.1 correlated with LY96, which plays a vital role in tumorigenesis by modulating host immunity." (PMID 36313374, 2022). "As Th9 cells play important roles in auto- and anti-tumor immunity, our studies suggest that therapeutic targeting IL-1β/IL-1R1 signaling may be beneficial in dampening Th9-mediated inflammation or may be bolstered to enhance tumor clearance." (PMID 36389679, 2022). "Interestingly, we also detected high levels of IL-1R1 expression in human HNSCC tumor infiltrating myeloid cells as well as murine macrophages post efferocytosis in vitro." (PMID 36439171, 2022). "Furthermore, we mined publicly available scRNA-seq datasets, and found that among intratumoural T cells, expression of IL1R1 transcript was largely restricted to Treg cells and was detected across 19 different tumour types." (PMID 35545675, 2022). "Moreover, using an MTT proliferation assay we found that tumour cells overexpressing IL1R1 displayed reduced proliferation compared to control cells when stimulated with exogenous IL-1B." (PMID 34290237, 2021). "We found that the growth of IL-1B overexpressing primary tumours was increased in IL1R1−/− mice compared to IL1R1fl/fl mice, suggesting that tumour-derived IL-1B can no longer exert its anti-tumour functions in IL1R1-deficient microenvironments." (PMID 34290237, 2021). "Interestingly, the IL-1R1 signaling pathway has been reported to promote tumor growth, angiogenesis and metastasis in some contexts, while stimulating anti-tumor immunity or directly suppressing tumorigenesis in others." (PMID 33031059, 2020). "Using disruption of IL1-R1 on different cell types in a mouse model, it was recently shown that IL-1R1 deficiency in epithelial cells reduces tumorigenesis in an APC model, while IL1-R1 deficiency in neutrophils increases bacterial invasion and tumor aggressiveness." (PMID 32635472, 2020). "By reconstructing the tumor microenvironment using ER+BCCs, TAFs, and the immune cells from the same primary tumors, we demonstrate that the effectiveness of endocrine therapy (Tam) can be significantly augmented in the presence of IL1R1 and PDGFRβ blockers." (PMID 31419632, 2019). "IL-1β increased tumor progression in mouse tumors, using IL-1β or IL-1R1 gene targeted mice." (PMID 31557902, 2019). "Limited studies have reported their utility and reproducibility in clinical practice and our co-expression study for Snail and Slug has identified a unique marker, IL1R1, to be highly expressed in these two subgroups and correlated with higher tumor cell proliferation rates." (PMID 30464804, 2018). "In addition to promoting tumour progression, by controlling Treg recruitment via CCL22 signalling, however, IL-1A mediated IL-1R1 signalling has also been reported to have anti-tumour functions." (PMID 29760166, 2018). "To determine which cells within the tumor might be responding to IL-1 stimulation, we performed immunohistochemical analysis for IL-1R1 expression in specimens taken from patient skin metastases." (PMID 28450382, 2017). "Blocking IL-1R1 had the same effect on E0771 tumour growth in DIO mice." (PMID 27708283, 2016). "Acting via its receptor IL-1R1, which belongs to the interleukin-1 receptor/Toll-like receptor superfamily, IL-1α exerts multiple effects in the tumor stroma, several of which are tumor-promoting." (PMID 27473228, 2016). "Expression of IL-1R1, however, has to be viewed in the context of IL-1R2 expression, which, according to our in situ hybridization patterns, was present in stronger signal intensities and in larger proportions of tumor cells than expression of IL-1R1." (PMID 26406983, 2015). "Therefore, the role of the host's IL-1β receptor-mediated signalling in tumour growth was further studied in Il1r1−/− mice." (PMID 23065753, 2012).